RUVBL1 (RuvB like AAA ATPase 1)
Diseases named in the same sentence as RUVBL1 in open-access papers (continued):
Sharing a sentence is not in itself a finding about the gene and the disease.
infection (5 papers, 2014 to 2024). The state of being infected such as from the introduction of a foreign agent such as serum, vaccine, antigenic substance or organism. "Mutants deleted for this region are unable to efficiently suppress interferon and part of the observed growth deficiency, particularly apparent at 96 h after infection, may be caused by loss of binding to RuvBL1." (PMID 29257057, 2017). "Our previous studies in HT1080 cells have shown that HAdV-C5 is reliant on RuvBL1 for efficient suppression of ISGs during infection." (PMID 38940561, 2024). "Expression of RuvBL1 at both RNA and protein levels were detected in our study, and they remained stable during infection." (PMID 30642258, 2019). "Indeed, infection with HAdV-C2 and HAdV-B7 seems to greatly reduce the binding of RuvBL1 to RNA polymerase II, while infection with HAdV-B14 significantly reduces it." (PMID 38940561, 2024). "Nevertheless, these results clearly demonstrate that RuvBL1 is retained or stabilized in high molecular weight complexes to a greater degree with species B infection versus HAdV-C2, suggesting that this complex may impair ISG expression." (PMID 38940561, 2024). "Since WNV is a neurotropic virus we tested whether RUVBL1 restricted infection in primary neuronal cultures." (PMID 24550726, 2014). "Therefore, we wanted to determine whether infection with HAdVs affects the ability of RuvBL1 to interact with RNA polymerase II or RuvBL2." (PMID 38940561, 2024). "Infection of human lung A549 cells with PR8 virus resulted in a reduction of the protein levels of RuvBL2 but not RuvBL1." (PMID 34072766, 2021). "Loss of RUVBL1, RUVBL2, or TIP60 mosquito orthologs did not affect cell number but led to a significant increase in WNV-KUN infection (p<0.05)." (PMID 24550726, 2014). "However, when we investigated the proportion of RuvBL1/2, on a global scale early in infection, in nuclear and cytoplasmic fractions we did not observe a difference, likely due to a relatively low number of cells infected at that stage of infection." (PMID 38940561, 2024). "In contrast to RuVBL2, the infection had no apparent effect on RuvBL1 protein levels." (PMID 34072766, 2021).
connective tissue diseases (2 papers, 2021 to 2023). "Indeed, SSc-specific autoantibodies recognize the epitopes present on the native RuvBL1/2 complex, while the autoantibodies detected in patients with other connective tissue diseases react with epitopes present on recombinant rRuvBL1 and/or rRuvBL2 fragments, but not on the native complex." (PMID 35716254, 2023).
RUVBL1 also shares sentences with these, for which no sentence is quoted: B-cell lymphoma (2 papers); ciliopathy (2); colorectal tumor (2); melanoma (2); Askin tumor (1); bladder cancer (1); Burkitt lymphoma (1); cardiac hypertrophy (1); cervical squamous cell carcinoma (1); glioma (1); hilar cholangiocarcinoma (1); Kidney Cyst (1); malaria (1); metastasis (1); pancreatic ductal adenocarcinoma (1); polymyositis (1); primitive neuroectodermal tumor (1); prostate tumor (1); salivary gland cancer (1); Seckel syndrome (1); thymoma (1).